VDAC2 (voltage dependent anion channel 2)
Diseases named in the same sentence as VDAC2 in open-access papers (continued):
Sharing a sentence is not in itself a finding about the gene and the disease.
lung carcinoma (4 papers, 2022 to 2024). "The 8 FRGs (ACSL3, FADS2, GLS2, HSF1, PANX1, PHKG2, VDAC2, and CDKN1A) that we selected to be associated with the diagnosis and prognosis of lung cancer have been shown to play important roles in cancer and tumor immunity." (PMID 38743344, 2024). "Nedd4 was found to be involved in ferroptosis along with VDAC2 in lung cancer." (PMID 38634270, 2024). "Immunofluorescence results showed that VDAC2 protein expression was significantly increased in lung cancer tissues compared to adjacent noncancerous tissues." (PMID 38382091, 2024).
dilated cardiomyopathy (3 papers, 2021 to 2025). Cardiomyopathy which is characterized by dilation and contractile dysfunction of the left and right ventricles. "VDAC2 is essential to cardiac function, as embryonic knockout of VDAC2 is embryonically lethal, and a cardiac-specific deletion of VDAC2 results in dilated cardiomyopathy, fibrosis, and alterations in calcium handling and action potentials." (PMID 40869375, 2025). "Shankar and co-workers successfully performed cardiac-specific Vdac2 knockout mice and demonstrated that, VDAC2-KO mice exhibited progressive deterioration of cardiac function and eventually developed dilated cardiomyopathy (DCM)." (PMID 35118147, 2021).
nasopharyngeal carcinoma (3 papers, 2023 to 2025). A carcinoma arising from the nasopharyngeal epithelium. "TRIM21 promoted degradation of mitochondrial voltage-dependent anion-selective channel protein 2 (VDAC2) through K48-linked ubiquitination in nasopharyngeal carcinoma, thereby inhibiting type I interferon response after radiotherapy in nasopharyngeal carcinoma." (PMID 39543140, 2024).
ovarian carcinoma (3 papers, 2022 to 2024). A malignant neoplasm originating from the surface ovarian epithelium. "TRIM8 degraded VDAC2 through the ubiquitination pathway, increased the resistance of ovarian cancer cells to iron death, and promoted the proliferation and migration of ovarian cancer." (PMID 38881325, 2024). "Knockdown of VDAC2 increased the resistance of ovarian cancer cells to iron death, whereas overexpression of VDAC2 attenuated ovarian cancer progression induced by TRIM8 overexpression." (PMID 38881325, 2024). "This study is the initial demonstration of the cancer‐promoting effects of TRIM8 in ovarian cancer by means of a distinct mechanism that involves the regulation of VDAC2." (PMID 38881325, 2024). "TRIM8 promotes ovarian cancer proliferation and migration by targeting VDAC2 for ubiquitination and degradation, these finding may provide new targets for the treatment of ovarian cancer." (PMID 38881325, 2024). "The OS of ovarian cancer patients prolonged with the high-expression of ATG7, G6PD, SLC3A2, MAP1LC3C and PTGS2, but shrank with the increased expression of NFS1, VDAC2, ACSL3." (PMID 35039008, 2022). "In addition, through the literature review, we found that except CYBB, VDAC2, IDH1, MT1G, SLC1A4, PCK2, SLC3A2, the prognostic value of other FRGs in ovarian cancer has been reported, which provided a possibility for constructing a prognostic model." (PMID 36386203, 2022).
pancreatic cancer (3 papers, 2020 to 2025). "Other examples of extramitochondrial regulation are the upregulations of VDAC-1 and VDAC-2 in the plasma membrane of human pancreatic cancer cells and of pl-VDAC-2 upon iron deprivation in erythroleukemia K562 cells." (PMID 40649921, 2025). "Targeting IFIT3/VDAC2 may represent a novel strategy to sensitize aggressive forms of pancreatic cancer to conventional chemotherapy regimens." (PMID 32641986, 2020). "Targeting IFIT3/VDAC2 may represent a potential strategy to re-sensitize aggressive pancreatic cancer to conventional chemotherapy regimens." (PMID 32641986, 2020).
pancreatic ductal adenocarcinoma (3 papers, 2024 to 2025). An infiltrating adenocarcinoma that arises from the epithelial cells of the pancreas. "Inflammatory interferon-induced protein with tetratricopeptide repeats 3 (IFIT3) regulates voltage-dependent anion channel 2 (VDAC2) O-GlcNAcylation and promotes the gemcitabine and paclitaxel resistance in pancreatic ductal adenocarcinoma cells." (PMID 40740652, 2025).
renal carcinoma (3 papers, 2025). A carcinoma arising from the epithelium of the renal parenchyma or the renal pelvis. "As a partner of the stimulator of interferon response cGAMP interactor 1, VDAC2 participates in nonclassical innate immune signaling regulated by STING, influencing the growth of renal cancer cells." (PMID 40626007, 2025).
Sepsis (3 papers, 2023 to 2025). Sepsis is defined as life-threatening organ dysfunction caused by a dysregulated host response to infection. "Malonyl-CoA was identified as the primary inducer of VDAC2 malonylation in sepsis, and treatments that lowered malonyl-CoA or blocked the malonylation site on VDAC2 were shown to be protective." (PMID 41107644, 2025). "In other words, Kmal of VDAC2 impairs mitochondrial permeability and metabolism, contributing to cardiomyocyte death during sepsis." (PMID 41107644, 2025). "The results indicated that TPP-AAV was superior to AAV (K46Q) in reducing ferroptosis and myocardial injury after sepsis by inhibiting VDAC2 malonylation." (PMID 37416771, 2023). "We discovered for the first time that malonyl-CoA upregulation after sepsis can increase VDAC2 malonylation." (PMID 37416771, 2023). "In summary, the present study revealed that the malonylation of K46 in VDAC2 is a novel mechanism in sepsis induced myocardial dysfunction." (PMID 37416771, 2023). "The regulation of VDAC2 malonylation can significantly impact mitochondrial-related ferroptosis and myocardial injury after sepsis." (PMID 37416771, 2023). "Indeed, overexpressing SIRT5 in cardiomyocytes has been shown to reverse VDAC2 hypermalonylation and reduce sepsis-induced ferroptosis, further validating this approach." (PMID 41107644, 2025). "Lys46 (K46) of VDAC2 was found to be highly conserved in different species, ranging from Human to Sheep, and the immunoblotting results confirmed that malonylated VDAC2 levels were increased in sepsis as compared with control." (PMID 37416771, 2023). "The malonyl-CoA was increased in sepsis rats and patients, which can induce VDAC2 malonylation." (PMID 37416771, 2023). "Our study revealed that cardiomyocytes display increased VDAC2 malonylation after sepsis." (PMID 37416771, 2023). "The volcano plot and heatmap indicated that JAK3, CHMP5 and IFNAR1 were upregulated while CASP8, VDAC2, FASLG, JAK1, STAT4 and BCL2 were downregulated in sepsis." (PMID 38894720, 2024). "After injection of AAV (K46E) or in the sepsis group, the levels of MDA and Fe2+ were significantly increased as compared with the control group, and down-regulation of VDAC2 malonylation by AAV (K46Q) decreased the levels of MDA and Fe2+ of heart tissues in sepsis rats." (PMID 37416771, 2023). "The study also found that the inhibition of VDAC2 malonylation by synthesizing mitochondria targeting nano material TPP-AAV could further alleviate ferroptosis and myocardial dysfunction following sepsis." (PMID 37416771, 2023). "Additionally, a mutant VDAC2 that could not be malonylated (K46Q mimicking a permanently unmodified state) was resistant to sepsis-induced dysfunction." (PMID 41107644, 2025).
atherosclerosis (2 papers, 2021 to 2025). A disease characterized by the build-up of fatty material and calcium deposition in the arterial wall resulting in partial or complete occlusion of the arterial lumen. "This signal colocalized with VDAC2 mRNA expression in multiple vascular tissues relevant to atherosclerosis, including aorta and tibial artery." (PMID 35186008, 2021).
Autoimmunity (2 papers, 2019 to 2021). The occurrence of an immune reaction against the organism's own cells or tissues. "The deregulation of VDAC2 is a possible trigger for the onset of autoimmunity, hence the elevation of VDAC2 antibodies might be the result of the overexpression of this protein, as well as apoptotic events." (PMID 30899261, 2019).
bladder cancer (2 papers, 2022 to 2025). "This study identified five prognostic biomarker genes related to mitochondrial function and programmed cell death in bladder cancer (POLB, FASN, CASP9, VDAC2, and RHOT2) and preliminarily constructed a prognostic model based on these genes." (PMID 41427247, 2025). "In this study, a novel prognostic model for bladder cancer was constructed based on POLB, FASN, CASP9, VDAC2, and RHOT2, which provided preliminary references for the prognostic evaluation of bladder cancer and subsequent studies related to its diagnosis and treatment." (PMID 41427247, 2025).
colon cancer (2 papers, 2013 to 2019). "Unlike VDAC1 removal, loss of VDAC2 or replacing its membrane-facing glutamate with glutamine renders human colon cancer cells largely resistant to ceramide-induced apoptosis." (PMID 31015432, 2019).
epilepsy (2 papers, 2022 to 2023). A brain disorder characterized by episodes of abnormally increased neuronal discharge resulting in transient episodes of sensory or motor neurological dysfunction, or psychic dysfunction. "Also, VDAC1 increase and VDAC2 decrease have been documented in epilepsy-related mitochondrial dysfunction." (PMID 36350974, 2022).
heart failure (2 papers, 2021 to 2025). Inability of the heart to pump blood at an adequate rate to meet tissue metabolic requirements. "Through this unique role in cellular calcium dynamics and excitation-contraction coupling VDAC2 emerges as a plausible therapeutic target for heart failure." (PMID 34321484, 2021). "A VDAC2 agonist, efsevin, rescued the heart failure phenotype, identifying a new potential therapeutic target for heart failure." (PMID 34321484, 2021). "Activation of VDAC2 by efsevin increased cardiac contractile force in a mouse model of pressure-overload induced heart failure." (PMID 34321484, 2021). "For instance, while the RCS of Vdac2, whose downregulation is one of the main responsible factors for heart failure, increased by 2.89× in the not-treated CCC mice (IN) with respect to the healthy animals (CN), it decreased in treated mice (IT) by 3.23×." (PMID 41296444, 2025).
neuroblastoma (2 papers, 2023 to 2025). Neuroblastoma (NB) is the most common solid, extracranial childhood tumor. "Similar results were observed using the human neuroblastoma cell line NMB as the administration of dopamine induced apoptosis, along with a reduction on the mRNA level for VDAC-1, VDAC-2, and VDAC-3." (PMID 40649921, 2025).
Parkinson disease (2 papers, 2025). A progressive degenerative disorder of the central nervous system characterized by loss of dopamine producing neurons in the substantia nigra and the presence of Lewy bodies in the substantia nigra and locus coeruleus. "Notably, both GLUD2 and VDAC2 encoded proteins have oral involvement in salivary glands and are associated with Parkinson’s disease, emphasizing metabolic complexity and its connection to neurodegenerative disorders in salivary gland dysfunction." (PMID 40806170, 2025). "In the VDAC2 KO cells, the highest magnitude loss was in the protein PLA2G6, a phospholipase, a gene for which loss of function results in a series of infantile neurodevelopmental disorders and Parkinson’s disease." (PMID 40568130, 2025).
thyroid carcinomas (2 papers, 2021 to 2024). "VDAC2 overexpression has been detected in 2 subtypes of differentiated thyroid carcinomas, and its silencing led to a better clinical response to chemotherapy." (PMID 39449743, 2024). "To explore the role of primary cilia in mitochondria-associated apoptosis in thyroid carcinomas, we examined expression of VDAC1, VDAC2, and VDAC3 mRNA in human PTC cells with or without ciliary loss." (PMID 33602982, 2021).
acute myeloid leukemia (1 paper, 2018). Acute myeloid leukemia (AML) is a group of neoplasms arising from precursor cells committed to the myeloid cell-line differentiation. "Moreover, the interaction with VDAC2 is critical for BAX to mediate cell death in response to chemotherapeutic agents both in vitro and in vivo, as well as for BAX to limit tumor development in a cMyc-driven model of acute myeloid leukemia (AML)." (PMID 30478310, 2018).
autoimmune disease (1 paper, 2024). A disorder resulting from loss of function or tissue destruction of an organ or multiple organs, arising from humoral or cellular immune responses of the individual to their own tissue constituents. "Excessive apoptosis is implicated in contributing to a range of disease states including autoimmune disease and acute or chronic neurodegenerative conditions, stabilising the VDAC2–BAK interaction may be a potential therapeutic strategy for inhibiting apoptosis in such settings." (PMID 38696533, 2024).
brain injuries (1 paper, 2018). "Disrupting the VDAC2:BAX interaction could be exploited to limit pathological apoptosis following traumatic or ischemic brain injuries since differentiated neurons lack functional BAK40." (PMID 30478310, 2018).
brain ischemia (1 paper, 2018). Diminished or absent blood supply to the brain caused by obstruction (thrombosis or embolism) of an artery resulting in neurologic damage. "Our results showed that brain ischemia and reperfusion caused the downregulation VDAC1 and VDAC3, whereas VDAC2 was least affected after global ischemia." (PMID 30305621, 2018).
brain tumors (1 paper, 2016). "This group also included proteins associated with metabolism and apoptosis, included proteins that were reported in other cancers, including liver and brain tumors, but not CLL, such as VDAC1, VDAC2, AIF and other mitochondrial proteins associated with metabolism and apoptosis regulation (group B)." (PMID 27078856, 2016).
cervical cancer (1 paper, 2016). A primary or metastatic malignant neoplasm involving the cervix. "To detect the expression of the candidate proteins in HPV16-positive cervical cancer tissues, we used IHC staining to assess the expression of VDAC1, VDAC2, VDAC3 and HPV16 E7." (PMID 27419626, 2016). "The expression of the other two members, VDAC2 and VDAC3, correlated with the metastasis of cervical cancer in the present study." (PMID 27419626, 2016).
cognitive decline (1 paper, 2020). "Regarding Vdac2, we are unable to resolve this contradiction between these two models although our results using folate restriction in a non-transgenic mouse may more accurately model the genetic changes occurring in cognitive decline in humans." (PMID 33282900, 2020).
endometrial cancer (1 paper, 2024). Primary or metastatic malignant neoplasm involving the endometrium (mucous membrane that lines the endometrial cavity). "Jóźwiak at al. have revealed that the high level of VDAC2 protein indicated a poor prognosis of endometrial cancer patients, which was consistent with our findings that NSCLC patients with overexpression of VDAC2 had worse prognosis." (PMID 38382091, 2024).
fibrosarcoma (1 paper, 2023). A malignant mesenchymal fibroblastic neoplasm affecting the soft tissue and bone. "Interestingly, a previous study found that RSL3 induces VDAC2 carbonylation in fibrosarcoma cells and counters its effect on ferroptosis." (PMID 37496319, 2023).
follicular adenoma (1 paper, 2024). "Comparative proteomics analysis using a high-performance liquid chromatography-tandem mass spectrometry approach revealed TSPAN30, DDB1, TYMP, VDAC2, and DCXR as the top five candidate biomarkers for directly comparing samples of follicular adenoma and normal thyroid tissue." (PMID 38649381, 2024).
gout (1 paper, 2024). A condition characterized by painful swelling of the joints, which is caused by deposition of urate crystals. "ROC curve analysis revealed that the presence of ACSL4, VDAC2, and GPX4 in urinary exosomes possesses substantial predictive value for acute gout attacks." (PMID 39606034, 2024). "In conclusion, our study analyzed the expression changes of ferroptosis-related proteins ACSL4, VDAC2, GPX4, and GSS in the urinary exosomes of gout patients." (PMID 39606034, 2024). "Moreover, ROC analysis in our study indicated that ACSL4, VDAC2, and GPX4 have strong predictive abilities for acute gout attacks, with AUC values of 0.771, 0.833, and 0.722, respectively." (PMID 39606034, 2024). "Specifically, changes in ferroptosis-related proteins such as ACSL4, VDAC2, GPX4, and GSS may serve as promising biomarkers for the monitoring of acute gout attacks." (PMID 39606034, 2024).
Huntington disease (1 paper, 2017). Huntington disease (HD) is a rare neurodegenerative disorder of the central nervous system characterized by unwanted choreatic movements, behavioral and psychiatric disturbances and dementia. "We also found many differentially expressed genes related to the Huntington disease (HD) pathway in both areas of the MPS II mouse model; among these, Bbc3, Bdnf, Crebbp, Dctn1, Dlg4, Gpx1, Grin1, Grin2b, Itpr1, and Pparg are up-regulated, while Dnaic2, Dnali1, Hap1, and Vdac2 are down-regulated." (PMID 28513549, 2017).
Immunodeficiency (1 paper, 2023). Failure of the immune system to protect the body adequately from infection, due to the absence or insufficiency of some component process or substance. "VDAC2 has not yet been recognised as a disease-causing gene, although it has been described to have a central role in determining thymocyte survival through its regulation of the pro-apoptotic protein, BAK2 and is therefore a possible candidate underlying the patient’s immunodeficiency." (PMID 37946251, 2023).
ischemic stroke (1 paper, 2018). A stroke disorder caused by obstruction of blood flow to the brain, due to thrombotic (local blood clot formation) or embolic (due to a blood clot or other material traveling from another site) event. "Moreover, si-VDAC2 and si-VDAC3 attenuated the postconditioning-induced neuroprotection, suggesting that stable presence of VDAC2 and VDAC3 also play important roles in neuronal survival after ischemic stroke." (PMID 30305621, 2018).
low grade glioma (1 paper, 2021). A grade I or grade II glioma arising from the central nervous system. "For example, VDAC2 was negatively associated with OS in low-grade glioma (LGG) and positively in pheochromocytoma and paraganglioma (PCPG)." (PMID 34434214, 2021).
pituitary adenoma (1 paper, 2024). "Differential expression of VDAC1, VDAC2, BAX and BAK genes according to pituitary adenoma size and invasiveness." (PMID 39449743, 2024).
prostate carcinoma (1 paper, 2017). A carcinoma that arises from epithelial cells of the prostate gland. "Other examples include arbutin (hydroquinone-O-beta-d-glucopyranoside), a tyrosinase inhibitor in A375 human malignant melanoma cells, and somatostatin, used in the treatment of advanced prostate cancer, which upregulated the expression of VDAC1 and VDAC2 in the LNCaP prostate cancer cell line." (PMID 28824871, 2017).
rheumatic diseases (1 paper, 2020). "Therefore, low density lipoprotein related protein 1 (LPR-1), thrombospondin-1 (TSP-1), voltage dependent anion channel 2 (VDAC2) and annexin A1 were chosen as proteins of special interest, based on literature data supporting their involvement in arthritic and rheumatic diseases." (PMID 32586320, 2020).
virus infection (1 paper, 2020). "In LCDV infection, we previously observed that the LCDV 32 kDa VAP interacts with VDAC2 and RACK1 receptors to initiate virus infection." (PMID 32630682, 2020).
xerostomia (1 paper, 2025). Dryness of the mouth resulting from reduced salivary secretion. "The downregulation of key proteins involved in oxidative stress and neurodegenerative diseases, encoded by PARK7, GLO1, GLUD2, VDAC2, UQCRC1, and UNC5C, including the 20S proteasome core complex proteins, highlights a possible mechanistic link to xerostomia pathophysiology." (PMID 40806170, 2025). "Akin to VDAC2, UQCRC1 emphasizes mitochondrial dysregulation to the progression of neurodegenerative diseases through dopaminergic neuronal degeneration, possibly related to the development of xerostomia." (PMID 40806170, 2025).